CD81 (CD81 molecule)
Diseases named in the same sentence as CD81 in open-access papers (continued):
Sharing a sentence is not in itself a finding about the gene and the disease.
sarcoma (4 papers, 2016 to 2023). A usually aggressive malignant neoplasm of the soft tissue or bone. "In our CLL cohort, CD5+CD19+CD27+ cells represented the discriminant phenotypic features of IL10+vs- and TGFβ1+vs- subsets, which also resembled CD19+CD81+CD27+CD25+PD-L1hi tumor evoked Bregs producing both IL10 and TGFβ1 in sarcomas." (PMID 36973425, 2023). "In contrast to neuroblastic tumors, soft tissue tumors and other extraosseous sarcomas—n = 20 (18%), with 19/20 infiltrated by MFC—had a common CD56++ CD271++ CD81++ phenotype in the absence of CD45, CD34, and EpCAM expression, with three distinct (heterogeneous) phenotypic profiles." (PMID 34638431, 2021).
acute myeloid leukemia (3 papers, 2021 to 2025). Acute myeloid leukemia (AML) is a group of neoplasms arising from precursor cells committed to the myeloid cell-line differentiation. "CD81 was implicated in B-cell and mantle cell lymphomas, acute lymphoblatic leukemia (ALL), and acute myeloid leukemia (AML)." (PMID 41211316, 2025).
asthma (3 papers, 2020 to 2024). "Previous studies have demonstrated that CD81 signaling plays an important role in promoting Th2 cells in asthma." (PMID 32258172, 2020). "CD81 expression in CD4+ T cells is induced by Th9-inducing factors during asthma attacks." (PMID 32258172, 2020). "Asthmatics BALF exosomes showed higher levels of tetraspanins CD81 and CD63, of HLA-DR, and CD36, a scavenger receptor with a potential role in asthma exacerbations in response to bacterial infections, compared to healthy controls." (PMID 38957448, 2024).
Autoimmunity (3 papers, 2022 to 2023). The occurrence of an immune reaction against the organism's own cells or tissues. "Of these, patients with CD19 and CD81 deficiency have also been reported to develop autoimmunity and autoimmune cytopenia have been reported in patients with CD81 deficiency." (PMID 35795667, 2022). "However, due to their significant increases in the tumor upon Flt3L treatment, the shift towards Tregs could be mediated via the increase in CD81+migcDC1s and migDCs as has previously been shown in the context of autoimmunity." (PMID 37622122, 2023). "Herein, we initially identified a set of 12 surface molecules, including CD39, CD229, CD81, CD326, CD54, CD130, CD49d, CD172a, CD274, CD155, CD205, and CD47 that are highly expressed by ASCs, and specifically identify ASCs in naive WT mice as well as in the contexts of immunization and autoimmunity." (PMID 35464469, 2022).
depression (3 papers, 2019 to 2025). "Importantly, the TNFR1/CD81 ratio was positively correlated with depression severity and symptomatology." (PMID 33430399, 2021).
emphysema (3 papers, 2018 to 2024). "CD9/CD81 knockout mice are more susceptible to developing emphysema and atrophy of various organs, including muscle, thymus and testis, and even shorten survival." (PMID 38725025, 2024). "Notably, CD9/CD81 DKO mice are more susceptible to cigarette-smoke-induced emphysema (manuscript in preparation)." (PMID 29572511, 2018). "Considering that CD9/CD81 DKO mice develop not only emphysema but also some of the extra-pulmonary diseases seen in COPD patients, such as body weight loss and osteoporosis, we regard these DKO mice as a novel model for human COPD32." (PMID 29572511, 2018). "We further demonstrated that Cd9/Cd81 double-knockout mice spontaneously developed pulmonary emphysema and that Cd9 likely performs protective roles in lung inflammation and emphysema." (PMID 33424923, 2020). "We found that CD9/CD81 DKO mice with the COPD-like phenotype progressively develop an accelerated aging syndrome, with symptoms including cataracts, osteoporosis, emphysema, and atrophy of the skin, muscle, and adipose tissue." (PMID 29572511, 2018). "Surprisingly, aged CD9/CD81 DKO mice developed not only emphysema but also non-pulmonary comorbidities such as osteoporosis and body weight loss, eventually leading to multiple aging phenotypes." (PMID 29572511, 2018).
Ewing sarcoma (3 papers, 2016 to 2025). A small round cell tumor that lacks morphologic, immunohistochemical, and electron microscopic evidence of neuroectodermal differentiation. "Importantly, increased ENO-1+ CD81+ EVs in the patient serum before treatments can distinguish patients with Ewing sarcoma from healthy individuals with an area under the curve of 0.92 and reflected the tumor burden in Ewing sarcoma patients during multidisciplinary treatments." (PMID 40679665, 2025).
fibrosarcoma (3 papers, 2020 to 2023). A malignant mesenchymal fibroblastic neoplasm affecting the soft tissue and bone. "A similar population, termed mDC1, has recently been identified in murine fibrosarcoma and was significantly reduced in Batf3 knock-out mice, corroborating our findings that CD81+migcDC1s originate from cDC1s." (PMID 37622122, 2023).
liver diseases (3 papers, 2013 to 2023). "CD81(CD81 Molecule) and CDKN1A (Cyclin Dependent Kinase Inhibitor 1A), the potential target genes of hsa-miR-3180, were located in liver diseases pathways." (PMID 37051592, 2023). "During HCV-mediated liver disease and HCC, the virus, and in particular its membrane glycoprotein E2, which binds CD81, was shown to mimic GPC3 in infected hepatocytes, thereby interfering with the GPC3/CD81 binding." (PMID 34065048, 2021).
Lupus (3 papers, 2022 to 2024). "CD81-overexpressed adeno-associated virus was intraperitoneally injected at the beginning of establishing the IMQ-induce lupus model." (PMID 35705919, 2022). "This is illustrated by the overexpression of CD79a and CD79b, molecules involved in the transduction of BCR signal, and of CD81 whose co-expression with BAFFR and CD38 in transitional B-cells is associated with active systemic lupus erythematosus." (PMID 39185406, 2024). "Taken together, the increase of apoptosis of MDSCs is directly correlated to CD81 signaling pathway in the treatment of lupus with HCQ." (PMID 35705919, 2022). "Meanwhile, when CD81 was over-expressed in lupus mice, the number of Th17 cells was reduced, and Treg cells expanded." (PMID 35705919, 2022). "CD81 was further confirmed to participate in the apoptosis of MDSCs and lupus disease progression by overexpressing CD81 in vivo." (PMID 35705919, 2022). "In summary, HCQ promoted the apoptosis of MDSCs by up-regulating the expression level of CD81 in MDSCs, and ultimately alleviated lupus symptoms." (PMID 35705919, 2022). "The results showed that the expression level of CD81 was significantly reduced in lupus mice, which suggested that CD81 might play a crucial role in the apoptosis of MDSC." (PMID 35705919, 2022). "In summary, CD81 could relieve the imbalance of Th17/Treg cells in IMQ-induced lupus mice, which might contribute to the regulation of the functions of MDSCs." (PMID 35705919, 2022). "In addition, we observed the effects of CD81 on Th17 and Treg cells, which CD81 overexpression recovered the increased proportion of Th17 cells and decreased proportion of Treg cells in blood and spleen of mice with lupus." (PMID 35705919, 2022). "HCQ recovered the expression level of CD81 in MDSCs of mice with lupus." (PMID 35705919, 2022). "Besides, CD81 overexpression alleviated the disease activity of lupus mice directly, as illustrated by improved indexes of pathology." (PMID 35705919, 2022). "Besides, the expression level of CD81 in purified MDSCs from murine spleens was also up-regulated in the HCQ-treated lupus group, compared with that in lupus group (P < 0.05)." (PMID 35705919, 2022). "CD81-overexpressed adeno-associated virus was intraperitoneally injected into the lupus mice." (PMID 35705919, 2022). "Hence, these findings demonstrated that HCQ could ameliorate lupus by inducing the apoptosis of MDSCs through upregulating the expression level of CD81, which further indicate the significance of MDSCs in lupus." (PMID 35705919, 2022).
oral cancer (3 papers, 2023). "With regard to CD81, the exosomes obtained from the oral fluids of oral cancer patients and healthy individuals showed a band at the expected 26 kDa area of the protein." (PMID 38059133, 2023). "Oral fluids collected from oral cancer patients (n=36) and health individuals (n=25) was evaluated for amount of exosomal proteins CD63, CD9 and CD81." (PMID 38059133, 2023). "Despite CD63, CD81, and CD9 are downregulated in patients with oral cancer (OC)." (PMID 37304135, 2023). "Therefore, a significantly reduced level of CD9 and CD81 expression, rather than an ambiguous increase in CD63 expression, can be used as an indicator of oral cancer, even in the early stages of the disease." (PMID 36707844, 2023).
osteoporosis (3 papers, 2013 to 2022). A condition of reduced bone mass, with decreased cortical thickness and a decrease in the number and size of the trabeculae of cancellous bone (but normal chemical composition), resulting in increased fracture incidence. "Moreover, mice doubly deficient in CD9 and CD81 spontaneously develop pulmonary emphysema and osteoporosis, a phenotype akin to human COPD." (PMID 24040034, 2013). "Therefore, we hypothesized that inhibiting the uptake of harmful BMSC-EVs by SCs by blocking CD81 on the membrane of EVs could prevent and treat patients with osteoporosis complicated with sarcopenia." (PMID 35846725, 2022). "Third, CD9/CD81 DKO macrophages are spontaneously activated and produce more MMP-9 than WT macrophages, and CD9/CD81 DKO mice suffer from age-related pulmonary emphysema and osteoporosis, phenotypes akin to human COPD." (PMID 24040034, 2013). "Blocking CD81 on the surface of senescent BMSC-EVs attenuates sarcopenia in aged mice, which could be useful for prevention of sarcopenia in patients with osteoporosis in clinical practice." (PMID 35846725, 2022). "And blocking CD81 on the surface of senescent BMSC-EVs could attenuate muscle atrophy in aged mice, which could be useful for prevention and treatment of sarcopenia in patients with osteoporosis in clinical practice." (PMID 35846725, 2022).
pancreatic cancer (3 papers, 2019 to 2023). "Conventional vesicles have high concentrations of tetraspanin proteins such as CD63, CD9, and CD81, in addition to Hsp70, which is a pancreatic cancer-specific marker that has also been reported in the exosomal or extravesicular population." (PMID 36002889, 2022). "Through our ELISA assay we measured levels of different exosome populations, in particular those carrying the ubiquitous CD9, CD81 and some markers already found in tumour exosomes of pancreatic cancer such as CD44v6, Tspan8, EpCAM, CD24, CXCR4, Integrins α6 and β4, CD133." (PMID 31048929, 2019).
periodontal disease (3 papers, 2020 to 2025). "The role of various subpopulations of sEVs from different tetraspanin proteins (CD63+, CD9+, CD81+ subtypes) in periodontal disease has not been widely investigated and requires further elucidation." (PMID 33670900, 2021).
plasma cell dyscrasia (3 papers, 2015 to 2024). "The expression of CD81 and CD56 on PCs using flow cytometry is considered routine immunophenotyping in the diagnosis and follow-up of patients with plasma cell dyscrasia." (PMID 38203720, 2023). "CD81 (TAPA-1), a ubiquitously expressed tetraspanin protein, participates in diverse biological activities including hepatitis C virus (HCV) infection, plasma cell dyscrasias, B lymphocyte function, cell proliferation, differentiation, and cell migration." (PMID 26266263, 2015).
sarcopenia (3 papers, 2018 to 2025). Progressive decline in muscle mass due to aging which results in decreased functional capacity of muscles. "Therefore, inhibiting EV uptake through blockade of CD81 with CD81‐specific siRNA or an anti‐CD81 antibody attenuated sarcopenia in aged mice." (PMID 40290901, 2025). "Thus, the treatment effect of anti-CD81 Ab on sarcopenia in vivo might be partly due to that anti-CD81 Ab influenced the macrophages in the muscle." (PMID 35846725, 2022). "Therefore, the osteopenia and sarcopenia seen in DKO mice cannot simply be attributed to the spill-over effect from the lung, but must involve disorganization of the fusion machinery after CD9/CD81 depletion." (PMID 29572511, 2018).
Stroke (3 papers, 2018 to 2025). Sudden impairment of blood flow to a part of the brain due to occlusion or rupture of an artery to the brain. "The genes Apoe, Cd81, and Fabp5 showed complementarity in enrichment in the stroke infarct site in the subacute stage across all four platforms." (PMID 38383565, 2024). "RNAScope validated the cross-platform analysis and confirmed that astrocytes contribute to an Apoe, Cd81, and Fabp5-rich signature within the stroke infarct site." (PMID 38383565, 2024). "The 10X Visium, 10X Chromium, and tDISCO analyses generated a list of interesting candidate transcripts that appeared to be differentially expressed in astrocytes proximal and distal to stroke injury, including the candidate genes, Apoe, Fabp5, Clu, Aldoc, and Cd81." (PMID 38383565, 2024).
triple-negative breast carcinoma (3 papers, 2022 to 2023). An invasive breast carcinoma which is negative for expression of estrogen receptor (ER), progesterone receptor (PR), and human epidermal growth factor receptor 2 (HER2). "Several monoclonal antibodies anti-CD81 have been developed, notably mAb 5A6 active against invasion and metastasis of triple-negative breast cancer cells." (PMID 37046846, 2023). "More recently, CD81 has been revealed to interact with CD44 to enhance the stemness of triple-negative breast cancer cells, and high CD81 expression can be found in circulating tumor cells." (PMID 36941633, 2023). "The same group showed that a unique anti-human CD81 antibody (5A6) effectively halts invasion and metastasis of triple-negative breast cancer cell lines." (PMID 36941633, 2023). "Kaplan–Meier plots of CD81 protein expression in patients with triple negative breast cancer (TNBC) correlate with an unfavorable overall survival (A), relapse-free survival (B), and distant-metastasis-free survival (C)." (PMID 36193887, 2022). "In addition, CD81 has been reported to ensure the membrane integrity of exosomes, which are capable of inducing stemness in triple-negative breast cancer." (PMID 36941633, 2023). "CD81 interacts with CD44 on the membrane and promotes mammosphere formation of triple negative breast cancer (TNBC) cells." (PMID 36193887, 2022). "Using protein structure modeling and interface prediction-guided mutagenesis, we demonstrate that membrane CD81 interacts with CD44 through their extracellular regions in promoting tumor cell cluster formation and lung metastasis of triple negative breast cancer (TNBC) in human and mouse models." (PMID 36193887, 2022).
acute leukemia (2 papers, 2023). A clonal (malignant) hematopoietic disorder with an acute onset, affecting the bone marrow and the peripheral blood. "Anemia is the most common symptom in acute leukemia, with 100% of patients presenting with anemia, in the CD81-positive AML group, the mean Hb concentration was 70.38±17.82, which was lower than that in the CD81-negative AML group." (PMID 37309539, 2023).
acute lymphoblastic leukemia (2 papers, 2020 to 2023). Leukemia with an acute onset, characterized by the presence of lymphoblasts in the bone marrow and the peripheral blood. "The situation is more favorable in acute lymphoblastic leukemia (ALL) with a clearly defined role for CD81." (PMID 37046846, 2023). "Molecules selectively targeting CD81 could be of prime interest to treat different onco-malignancies, including B-cell and mantle cell lymphomas, acute lymphoblastic leukemia (ALL) and perhaps AML." (PMID 37046846, 2023). "In acute lymphoblastic leukemia (ALL), azacitidine (DNMTi) and panobinostat (HDACi) combined to disrupt cellular adhesion within the bone marrow microenvironment in ALL by decreasing the surface expression of the tetraspanin protein CD81, resulting in increased chemosensitivity." (PMID 32670880, 2020).
acute megakaryoblastic leukemia (2 papers, 2022 to 2025). Acute megakaryoblastic leukemia (AMKL) is a form of acute myeloid leukemia (AML) that occurs predominantly in childhood and particularly in children with Down syndrome (DS-AMKL). "In this article, we hypothesize that CD81 may play a vital role in acute megakaryoblastic leukemia (AMKL)." (PMID 41211316, 2025). "It has been reported that CD81 is overexpressed in non-Down syndrome acute megakaryoblastic leukemia (non-DS AMKL)." (PMID 41211316, 2025).
chronic obstructive pulmonary disease (2 papers, 2017 to 2024). A chronic and progressive lung disorder characterized by the loss of elasticity of the bronchial tree and the air sacs, destruction of the air sacs wall, thickening of the bronchial wall, and mucous accumulation in the bronchial tree. "For example, CD9 and CD81 share 45% identity, and double-deficient mice have macrophage dysfunction leading to a phenotype that resembles chronic obstructive pulmonary disease; neither single knockout has detectable disease." (PMID 28032533, 2017). "CD9 and CD81 are two widely distributed and closely correlated TM4SFs, which can play preventive roles in systemic inflammation of chronic obstructive pulmonary disease (COPD)." (PMID 38725025, 2024).